EZR (ezrin)
Description:
Probably involved in connections of major cytoskeletal structures to the plasma membrane. In epithelial cells, required for the formation of microvilli and membrane ruffles on the apical pole. Along with PLEKHG6, required for normal macropinocytosis.
Synonyms: VIL2; CVIL; CVL; HEL-S-105
Tractability: Antibody: UniProt places it where antibodies can reach, with high confidence; its Gene Ontology location is reachable by antibodies, with high confidence; the Human Protein Atlas places it where antibodies can reach. PROTAC: ubiquitination databases record sites on it; its protein half-life has been measured; a small molecule that binds it is known.
Target class: Structural protein
Gene: Protein-coding gene on chromosome 6 (158,765,741 to 158,819,413, reverse strand). Ensembl gene ENSG00000092820.
Subcellular location: Apical cell membrane; Cell projection; Cell projection, microvillus membrane; Cell projection, ruffle membrane; Cytoplasm, cell cortex; Cytoplasm, cytoskeleton; Cell projection, microvillus
Subcellular location (Human Protein Atlas): Plasma membrane
Pathways (Reactome):
Developmental Biology: Netrin-1 signaling; Recycling pathway of L1
Sensory Perception: Sensory processing of sound by inner hair cells of the cochlea; Sensory processing of sound by outer hair cells of the cochlea
Gene Ontology:
Molecular function: actin binding; actin filament binding; ATPase binding; cadherin binding; cell adhesion molecule binding; identical protein binding; microtubule binding; protein binding; protein domain specific binding; protein kinase A binding; protein kinase A catalytic subunit binding; protein kinase A regulatory subunit binding; RNA binding; S100 protein binding; cytoskeletal protein binding; disordered domain specific binding
Biological process: actin cytoskeleton organization; actin filament bundle assembly; astral microtubule organization; cAMP/PKA signal transduction; cortical microtubule organization; establishment of centrosome localization; establishment of endothelial barrier; establishment of epithelial cell apical/basal polarity; filopodium assembly; gland morphogenesis; leukocyte cell-cell adhesion; membrane to membrane docking; microvillus assembly; negative regulation of ERK1 and ERK2 cascade; negative regulation of p38MAPK cascade; negative regulation of T cell receptor signaling pathway; negative regulation of transcription by RNA polymerase II; positive regulation of early endosome to late endosome transport; positive regulation of gene expression; positive regulation of interleukin-2-mediated signaling pathway; positive regulation of protein catabolic process; positive regulation of protein localization to early endosome; protein localization to cell cortex; protein localization to plasma membrane; protein-containing complex localization; and 11 more
Cellular component: actin cytoskeleton; actin filament; apical part of cell; apical plasma membrane; cell periphery; cytoplasm; cytosol; endosome; extracellular exosome; extracellular region; filopodium; focal adhesion; immunological synapse; membrane; microvillus; perinuclear region of cytoplasm; plasma membrane; plasma membrane raft; protein-containing complex; ruffle; vesicle; adherens junction; basolateral plasma membrane; brush border; cortical cytoskeleton; and 6 more
Genetic constraint (gnomAD): Loss-of-function variants: 40 observed, 74.73 expected, observed/expected ratio (o/e) 0.54, 90% interval 0.41 to 0.7. The upper end of that interval is the gene's LOEUF score, 0.7, which puts it in group 2 of 6, group 1 being the genes least tolerant of losing a copy. Missense variants: 678 observed, 782.17 expected, observed/expected ratio (o/e) 0.87, 90% interval 0.81 to 0.92. Synonymous variants: 341 observed, 293.21 expected, observed/expected ratio (o/e) 1.16, 90% interval 1.06 to 1.27.
Cancer hallmarks: proliferative signalling (promotes); invasion and metastasis (promotes); escaping programmed cell death (promotes)
Homologues: Orthologues: chimpanzee EZR (99% identical), macaque EZR (98% identical), dog EZR (97% identical), mouse Ezr (96% identical), guinea pig EZR (96% identical), rat Ezr (96% identical), rabbit EZR (86% identical), tropical clawed frog ezr (81% identical), zebrafish ezrb (79% identical), zebrafish ezra (76% identical), pig EZR (75% identical). Paralogues in human: RDX (76% identical), MSN (73% identical), NF2 (46% identical), FRMD4B (25% identical), FRMD4A (24% identical), ERMN (12% identical).
Diseases named in the same sentence as EZR in open-access papers:
EZR is named in the same sentence as 255 diseases in open-access papers, as found by Europe PMC text mining. Sharing a sentence is not in itself a finding about the gene and the disease. The quoted sentences say what the papers report.
breast carcinoma (120 papers, 2005 to 2025). "Kaplan-Meier survival analysis in our study indicated that higher ezrin expression, both in terms of intensity and H score, was associated with poorer prognosis and reduced overall survival in breast cancer patients." (PMID 39827339, 2025). "In tumours from 377 breast cancer patients, high ezrin expression was significantly associated with adverse overall survival and disease‐free survival." (PMID 36938826, 2023). "High ezrin protein expression was significantly associated with shortened survival in a large cohort of early‐stage breast cancer patients." (PMID 36938826, 2023). "Associations between ezrin protein expression, determined in 1094 early‐stage breast cancer patients using immunohistochemistry, with clinicopathological variables." (PMID 36938826, 2023). "Studies have found that co‐culture of CAF with the conditioned medium of BRCA1‐deficient human breast cancer cells HCC1937 can increase the expression level of ezrin mRNA in CAF by 30‐fold, which helps tumor cells to metastasize and invade." (PMID 37171030, 2023). "High expression of ezrin mRNA (VIL2) in the METABRIC cohort was also significantly associated with adverse survival of breast cancer patients (p < 0.001)." (PMID 36938826, 2023). "High ezrin expression was significantly associated with adverse survival of breast cancer patients (p < 0.001)." (PMID 36938826, 2023). "Taken together, AJAP1-Ezrin+ was a potential risk factor for predicting breast cancer patients with poor prognosis." (PMID 35311087, 2022). "In our research, we found that AJAP1 expression was negatively linked with Ezrin expression and their combination can predict the prognosis of breast cancer." (PMID 35311087, 2022). "The adaptor protein ezrin has been shown to promote cancer metastasis in multiple preclinical models and is associated with poor prognosis in several cancer types, including breast cancer." (PMID 36923551, 2022). "We recently showed ezrin to be prognostic in patients with breast cancer who are at higher risk for disease relapse, consistent with preclinical data from our group and others linking ezrin with a metastatic-specific function." (PMID 36923551, 2022). "AJAP1 expression was negatively associated with Ezrin expression including the prognosis function for breast cancer patients." (PMID 35311087, 2022). "Unexpectedly, ezrin is essential for the basal and breast cancer cell-stimulated THP-1 expression of ITGAM mRNA that encodes integrin CD11b, critical for cell adhesion." (PMID 33086476, 2020). "Sex steroids, particularly estrogen can rapidly cause the membrane translocation of ezrin and ERα and formation of membrane ruffles as well as pseudopodia in endothelial and breast cancer cells." (PMID 30996241, 2019). "In particular, activation of ERM proteins triggers invasion and metastasis of breast cancer, and increased expression and abnormal distribution of ezrin have been associated with poor prognosis for breast cancer patients." (PMID 27029001, 2016). "For example, cytoplasmic expression of ezrin was associated with higher grade, hormonal-receptor negativity, and lymph-node metastases in breast cancer." (PMID 25580109, 2014). "In the present study we dissected the relationship between CD44 raft affiliation, ezrin association and migratory potential in breast cancer cells." (PMID 24512624, 2014). "We also found that nuclear expression of ezrin was associated with grade 3 (G3) breast cancer tumours (P = 0.015), thus confirming a potential role of nuclear ezrin immunodistribution in tumour development." (PMID 23420497, 2013). "Ezrin expression has also been linked to poor survival in several cancers, including carcinomas of the breast, endometrium, and ovary; cutaneous and uveal melanomas; and soft tissue sarcomas." (PMID 23357878, 2013). "Ezrin has been shown to be a key component in tumor metastasis and is associated with metastatic potential and poor outcome in breast carcinomas." (PMID 20858276, 2010).
breast carcinoma (continued). "We therefore examined the effect of amino-terminal ezrin on invasion and dissemination of a highly metastatic mammary carcinoma variant cell line, namely AC2M2, which is derived from SP1 cells." (PMID 15987432, 2005). "Ezrin expression is associated with clinical outcome of breast cancer patients." (PMID 36938826, 2023). "Ezrin expression is associated with more aggressive disease and may have clinical utility as a biomarker of patient prognosis in early‐stage breast cancer." (PMID 36938826, 2023). "Many studies showed that ezrin is involved in the regulation of focal adhesion and invadopodia dynamics, and its overexpression is associated with metastasis of various cancers including breast cancer." (PMID 32679794, 2020). "We hypothesize that the interaction between ezrin and P65 is associated with the activation of the NF-κB pathway leading to breast cancer metastasis." (PMID 31827401, 2019). "Data from our laboratory and other groups have shown that ezrin overexpression in breast cancer cells increases cell scattering and invasion, whereas knockdown or mutational inactivation of ezrin reduces cancer cell migration and diminishes the metastatic potential of cancer cells." (PMID 30678714, 2019). "The novel role for ezrin in the regulation of tumour lymphangiogenesis is consistent with previous clinical reports suggesting a strong association between ezrin and positive LN status in breast cancer." (PMID 25231728, 2014). "Furthermore, the correlation analysis between continuous AQUA scores and dichotomized clinicopathological data revealed that high expression of Src and ezrin were significantly associated with LVI in breast cancer (respectively)." (PMID 25231728, 2014). "Interestingly, a shift from apical membrane to cytoplasmic expression of ezrin has been associated with dedifferentiation, invasiveness, and poor prognosis in colorectal, head & neck and breast cancer." (PMID 24086451, 2013). "In addition, ectopic expression of the suppressor gene, RhoBTB2, causes dephosphorylation of ezrin and inhibits migration and metastasis of breast carcinoma cells." (PMID 22397367, 2012). "Ezrin has been linked to metastasis in human breast carcinoma, human OS, and a mouse model of OS." (PMID 23346460, 2012). "Moreover, ezrin expression was shown to be strongly associated with poor prognosis in breast carcinoma." (PMID 19680458, 2010). "In addition to assessing protein expression, this study also demonstrated that high ezrin mRNA expression (VIL2) was associated with shortened disease‐specific survival of breast cancer patients using the METABRIC cohort, which supports our results at the protein level." (PMID 36938826, 2023). "Ezrin, a member of the ezrin/radixin/moesin family of proteins linking plasma membrane to cytoskeleton actins, is transported along with the microvesicular cargo and determine P-gp membrane insertion through a cytoskeletal association, as shown in breast cancer cells." (PMID 30925930, 2019). "Ezrin expression has been found to be positively related to the degree of malignancy in many tumors, and its expression has also been linked to poor survival in several cancers, including carcinomas of the breast, endometrium and in melanomas and soft tissue sarcomas." (PMID 26933912, 2016). "By profiling of primary breast tumors, tumor associated normal tissue and breast cancer cell lines using RQ-PCR, as well as functional assays, it was demonstrated that miR-183 targets ezrin and may play a central role in the regulation of migration and metastasis in breast cancer." (PMID 22408395, 2012). "Studies have demonstrated that silencing ezrin results in breast cancer cells adopting an epithelial morphology and losing their migratory ability." (PMID 39827339, 2025). "The relocation of ezrin from the apical membrane in normal breast epithelial cells to the cytoplasm in invasive breast cancer cells suggests a functional role of ezrin in promoting tumor invasion and metastasis." (PMID 39827339, 2025).
breast carcinoma (continued). "Together, these data demonstrate correlations and co-localization between ERBB2, SLC9A3R1 and EZR gene expression early during the development of HER2-positive breast cancer." (PMID 40390040, 2025). "Our study revealed a significant but weak correlation between PTHrP and ezrin expression in breast cancer tissue." (PMID 39827339, 2025). "Ezrin is believed to facilitate breast cancer cell migration and invasion through the induction of EMT." (PMID 39827339, 2025). "PTHrP and ezrin have emerged as potentially significant biomarkers in several cancers, including breast cancer." (PMID 39827339, 2025). "Further research is needed to investigate whether the co-expression of PTHrP and ezrin has a synergistic or additive effect on tumor behavior and metastasis and to elucidate the underlying mechanisms of their interaction and their combined impact on breast cancer progression." (PMID 39827339, 2025). "Our findings highlight the significant roles of PTHrP and ezrin in breast cancer progression and prognosis." (PMID 39827339, 2025). "In breast cancer, Ezrin was found to be required for initial seeding and colonization at distant organ sites, such as in the lungs." (PMID 37371090, 2023). "Multivariate Cox regression analysis showing ezrin protein expression, various pathological variables and their effect upon disease‐specific survival in breast cancer patients (A), and in hormone receptor‐positive patients (B)." (PMID 36938826, 2023). "Ten‐year survival of breast cancer patients with low expression of ezrin was 76.5% (95% confidence interval (CI) = 0.736–0.794), while survival for those with high expression of ezrin was 64.7% (95% CI = 0.584–0.710)." (PMID 36938826, 2023). "Specifically, breast cancer cells use a PODXL–Ezrin signaling axis to rearrange the cytoskeleton and create a dorsal cortical polarity, changing cancer cells from a non-polarized rounded morphology to an invasive extravasation shape." (PMID 37371090, 2023). "Previous studies have investigated ezrin protein expression in smaller cohorts of breast cancer patients, or patients with specific disease characteristics, such as triple‐negative disease, to show associations with clinical outcomes." (PMID 36938826, 2023). "While the clinical and prognostic value of ezrin has been previously evaluated in breast cancer, most studies to date have been conducted in smaller cohorts (less than 500 cases) or have focused on specific disease characteristics." (PMID 36938826, 2023). "Expression of ezrin mRNA has been previously assessed in breast cancer, with high expression within the TCGA patient cohort associated with poor overall survival, in support of these findings." (PMID 36938826, 2023). "Expression of ezrin mRNA has also been assessed in breast cancer, with high expression within the TCGA patient cohort associated with poor overall survival." (PMID 36938826, 2023). "Ezrin expression is greatly increased in breast cancer cells and involved in regulating breast cancer cell proliferation, apoptosis, adhesion, invasion, metastasis, and angiogenesis." (PMID 37791063, 2023). "RhoA has also been shown to regulate breast cancer metastasis as an upstream signaling factor of Ezrin, where increasing RhoA phosphorylation resulted in enhanced Ezrin expression." (PMID 37371090, 2023). "The current study is the largest of its kind to evaluate ezrin both at the protein and mRNA levels in early‐stage breast cancer patients using the Nottingham (n = 1094) and METABRIC (n = 1980) cohorts, respectively." (PMID 36938826, 2023). "This Ezrin dependence was further corroborated in breast cancer cells when studying the role of PODXL in tumor cell extravasation, which curiously reported the PODXL extracellular domain as dispensable for extravasation." (PMID 36735782, 2023).